CDC34 (cell division cycle 34, ubiquitin conjugating enzyme)
Description:
E2 ubiquitin-conjugating enzyme that accepts ubiquitin from an E1 ubiquitin-activating protein, and catalyzes its covalent attachment to other proteins by an E3 ubiquitin-protein ligase complex. In vitro catalyzes 'Lys-48'-linked polyubiquitination. Cooperates with the E2 UBCH5C and the SCF(FBXW11) E3 ligase complex for the polyubiquitination of NFKBIA leading to its subsequent proteasomal degradation. Performs ubiquitin chain elongation building ubiquitin chains from the UBE2D3-primed NFKBIA-linked ubiquitin. UBE2D3 acts as an initiator E2, priming the phosphorylated NFKBIA target at positions 'Lys-21' and/or 'Lys-22' with a monoubiquitin. Cooperates with the SCF(SKP2) E3 ligase complex to regulate cell proliferation through ubiquitination and degradation of MYBL2 and KIP1. Involved in ubiquitin conjugation and degradation of CREM isoform ICERIIgamma and ATF15 resulting in abrogation of ICERIIgamma- and ATF5-mediated repression of cAMP-induced transcription during both meiotic and mitotic cell cycles. Involved in the regulation of the cell cycle G2/M phase through its targeting of the WEE1 kinase for ubiquitination and degradation. Also involved in the degradation of beta-catenin. Is target of human herpes virus 1 protein ICP0, leading to ICP0-dependent dynamic interaction with proteasomes.
Synonyms: UBCH3; UBE2R1; E2-CDC34; UBC3
Tractability: Small molecule: a structure with a bound ligand is known; it has a high-quality binding pocket. PROTAC: UniProt records ubiquitination sites on it; ubiquitination databases record sites on it; its protein half-life has been measured.
Gene: Protein-coding gene on chromosome 19 (531,721 to 542,092, forward strand). Ensembl gene ENSG00000099804.
Subcellular location: Cytoplasm; Nucleus
Subcellular location (Human Protein Atlas): Nuclear speckles; Nucleoplasm; Cytosol
Pathways (Reactome):
Immune System: Antigen processing: Ubiquitination & Proteasome degradation; CLEC7A (Dectin-1) signaling; Downstream TCR signaling; FCERI mediated NF-kB activation
Metabolism of proteins: Synthesis of active ubiquitin: roles of E1 and E2 enzymes
Gene Ontology:
Molecular function: protein binding; ubiquitin conjugating enzyme activity; ubiquitin-protein transferase activity
Biological process: cellular response to interferon-beta; proteasome-mediated ubiquitin-dependent protein catabolic process; protein K48-linked ubiquitination; protein polyubiquitination; protein ubiquitination; DNA replication initiation; G1/S transition of mitotic cell cycle; protein modification process
Cellular component: cytosol; nuclear speck; nucleoplasm; nucleus; cytoplasm
Genetic constraint (gnomAD): Loss-of-function variants: 18 observed, 23.5 expected, observed/expected ratio (o/e) 0.77, 90% interval 0.53 to 1.14. The synonymous counts are far from expectation, so gnomAD's model fits this gene poorly and the ratio says little. Missense variants: 280 observed, 307.65 expected, observed/expected ratio (o/e) 0.91, 90% interval 0.82 to 1. Synonymous variants: 178 observed, 134.84 expected, observed/expected ratio (o/e) 1.32, 90% interval 1.17 to 1.5.
Homologues: Orthologues: macaque CDC34 (99% identical), mouse Cdc34 (99% identical), rat Cdc34 (99% identical), chimpanzee CDC34 (99% identical), dog CDC34 (99% identical), pig CDC34 (98% identical), mouse Cdc34b (91% identical), guinea pig CDC34 (90% identical), tropical clawed frog cdc34 (78% identical), rabbit CDC34 (55% identical). Paralogues in human: UBE2R2 (81% identical), UBE2G1 (39% identical), UBE2G2 (33% identical), UBE2I (26% identical), UBE2B (25% identical), UBE2N (25% identical), UBE2A (24% identical), UBE2T (24% identical), UBE2C (23% identical), UBE2K (23% identical), UBE2NL (23% identical), UBE2O (23% identical), and 12 more.
Diseases named in the same sentence as CDC34 in open-access papers:
CDC34 is named in the same sentence as 24 diseases in open-access papers, as found by Europe PMC text mining. Sharing a sentence is not in itself a finding about the gene and the disease. The quoted sentences say what the papers report.
lung carcinoma (6 papers, 2009 to 2025). "Over-expression of let-7 miRs alters cell cycle progression and reduces cell division in lung cancer cells and causes cell cycle arrest by directly regulating the gene Cdc34 in human fibroblasts." (PMID 19517021, 2009). "Knockdown of CDC34 can inhibit the growth and survival of lung cancer cells, while overexpression can promote the growth and survival of lung cancer cells." (PMID 40650277, 2025). "Knockdown of CDC34 inhibits cell growth and proliferation, whereas its overexpression promotes the growth and survival of lung cancer cells." (PMID 34199813, 2021). "The overexpression of CDC34 levels has been found in numerous human cancers, including lung cancer, hepatocellular carcinomas, and breast cancer." (PMID 34199813, 2021). "CDC34, which is upregulated in B-ALL EVs, is known to facilitate lung cancer progression, while NUF2, which is upregulated in the EVs of 6 of 8 B-ALL samples in this study, is known to facilitate the progression of lung adenocarcinoma." (PMID 38023151, 2023). "Numerous E2 enzymes (including CDC34, UBC9, UBE2C, UBE2D, UBE2N, UBE2S, and UBE2Z) have been shown to be significantly overexpressed in lung cancer, contributing to facilitating cell proliferation and tumor growth." (PMID 34502538, 2021). "CC0651, a small molecule inhibitor that selectively inhibits CDC34, potently suppresses cell proliferation of several human cancer cell lines; however, there is still a lack of preclinical or clinical information on CC0651 in lung cancer." (PMID 34502538, 2021).
breast carcinoma (3 papers, 2014 to 2024). "In the blue module, Cdc34 codes for a ubiquitin-conjugating enzyme that regulates cell cycle progression, while Cmas encodes a key enzyme (cytidine monophosphate N-acetylneuraminic acid synthetase) in the sialylation pathway that enhances invasion of breast cancer cells." (PMID 32831131, 2020). "On the other hand, let-7a inhibits the proliferation of human glioblastoma, human nonsmall cell lung tumor, Burkitt lymphoma, breast cancer cells, and primary fibroblasts, through the repression of Ras, c-myc, E2F1, and CDC34 as well as elevation of p21." (PMID 24165399, 2014).
head and neck squamous cell carcinoma (2 papers, 2018 to 2024). A squamous cell carcinoma that arises from any of the following anatomic sites: lip and oral cavity, nasal cavity, paranasal sinuses, pharynx, larynx, and salivary glands. "In head and neck squamous cell carcinoma cell lines, Niclosamide treatment resulted in an increase in let-7d and a decrease in the cell cycle regulator CDC34 expression, ultimately resulting in G1 phase arrest." (PMID 39191850, 2024). "In summary, our data suggest that niclosamide induces cell cycle arrest in G1 phase in head and neck squamous cell carcinoma through let-7/CDC34 axis." (PMID 30687101, 2018).
muscular atrophy (1 paper, 2017). The loss of muscle tissue due to inactivity or disease. "By contrast, UBE2R (CDC34) and UBE2G1 protein levels were upregulated after denervation, and these E2 enzymes could potentially modulate the function of E3 ligases during muscular atrophy." (PMID 28546288, 2017).
Obesity (1 paper, 2024). Accumulation of substantial excess body fat. "However, with obesity, we observed increased accessibility of genes involved in cell cycle regulation (ATM, CDKN1C, BCL2L11), autophagy (HSPA8, IRF8, PEX5), and protein catabolism (CDC34, CTSB, UBB)." (PMID 39872537, 2024).
cancer (9 papers, 2013 to 2021). A tumor composed of atypical neoplastic, often pleomorphic cells that invade other tissues. "The loss of IGF2BP1 inhibits Cdc34, Lin-28B, and K-Ras, suppresses cancer cell proliferation and anchorage-independent growth, and promotes caspase-mediated cell death." (PMID 34203267, 2021). "In this study, we explored a molecular mechanism through which niclosamide inhibits cancer cell proliferation in G1 phase arrest, through let-7d/CDC34 axis." (PMID 30687101, 2018). "The new findings broaden our understanding of the anti-cancer effect of niclosamide, and extend the role of niclosamide/let-7/CDC34 axis in developing cancer therapeutic approach." (PMID 30687101, 2018). "Inhibiting E2 enzyme activity with CDC34 could enhance the anti-cancer activity of bortezomib, dexamethasone and 2-methoxyestradiol." (PMID 23762443, 2013). "Moreover, it also selectively reduces the levels of other cancer-related IGF2BP1 mRNA targets including CALM1, CDC34, COL5A, and BTRC, similar to the effect by RNAi knockdown of IGF2BP1 both in IGROV-1 and SK-MEL2 cancer cells." (PMID 29954406, 2018).
tumor (8 papers, 2011 to 2025). "Downregulation was observed for the genes CCNG2 (−9.0-fold), CCND1 (−5.84-fold), TFDP1 (−5.84-fold), CDC34 (−5.14-fold), and HUS1 (−4.52-fold), which are normally linked to the development of various tumor types when overexpressed." (PMID 39337305, 2024). "An acidic insertion in the loop β2α4 has been identified in the proximity of the catalytic cysteine of several E2 enzymes, including Cdc34 that plays a major regulatory role in cell cycle progression and tumor development." (PMID 21637798, 2011). "Moreover, the inhibitor CC0651, targeting the E2 enzyme Cdc34, prevents the ubiquitination and degradation of p27, thus hindering tumor cell proliferation." (PMID 40697329, 2025). "Recently, CDC34 has emerged as a functional target of let-7 microRNA, which is a tumor suppressor." (PMID 34199813, 2021). "In the subnetwork related to tumor progression, the hubs from the blue module are the most connected, such as the genes Cmas, Kmt2a, Golt1b, Cdc34, Manf, Sco1, and Thoc3, followed by hubs from the light cyan (Extl2, Commd3, Wdr41, Keap1, Osbpl9) and pink modules." (PMID 32831131, 2020). "A tumor-suppressive function is exerted by IGF2BP1 too, which inhibits KRAS, CDC34, and MYC expression and promotes apoptosis." (PMID 33238574, 2020). "Luciferase assay was conducted to demonstrate the interaction between let-7d (a let-7 family member which functions as a tumor suppressor by regulating cell cycle) and 3′UTR of CDC34 mRNA." (PMID 30687101, 2018). "Furthermore, the immunohistochemistry results showed that niclosamide treatment markedly decreased the CDC34 and MCM2 positive-stained tumor cells compared to control group, which indicated that niclosamide blocked the initiation of DNA synthesis in S phase." (PMID 30687101, 2018).
infection (2 papers, 2017 to 2020). The state of being infected such as from the introduction of a foreign agent such as serum, vaccine, antigenic substance or organism. "Of these, UBC1, a ubiquitin E2, is related to T. brucei CDC34 (99% query cover, 55.2% identity, E value: 2e-105), required for cytokinesis and infection progression of bloodstream form parasites in mice." (PMID 33108402, 2020). "Notably, the observed requirement for UBC1/CDC34 during L. mexicana mouse infection mirrors the finding that TbCDC34 is required for infection of mice with bloodstream form T. brucei." (PMID 33108402, 2020). "The E2s UBC1/CDC34, UBC2 and UEV1 and the HECT E3 ligase HECT2 are required for the successful transformation from promastigote to amastigote and UBA1b, UBC9, UBC14, HECT7 and HECT11 are required for normal proliferation during mouse infection." (PMID 33108402, 2020).
CDC34 also shares sentences with these, for which no sentence is quoted: gastric cancer (3 papers); acute lymphoblastic leukemia (1); African sleeping sickness (1); B cell lymphoma (1); Burkitt lymphoma (1); glioblastoma (1); hematological malignancies (1); hepatocellular carcinoma (1); leukemia (1); lung adenocarcinoma (1); lymphoma (1); melanoma (1); myeloma (1); ovarian carcinoma (1); renal carcinoma (1); T-cell acute lymphoblastic leukemia (1).